CXCL12 (C-X-C motif chemokine ligand 12)
Diseases named in the same sentence as CXCL12 in open-access papers (continued):
Sharing a sentence is not in itself a finding about the gene and the disease.
sarcoma (5 papers, 2011 to 2025). A usually aggressive malignant neoplasm of the soft tissue or bone. "When analyzing all sarcomas unsegregated by diagnosis, we found that patients with high CXCL12 levels had shorter OS than those with low levels (p = 0.0040)." (PMID 41008853, 2025). "The CXCL12/CXCR4 axis showed an intense coexpression in both sarcomas at all times throughout the experience." (PMID 28386296, 2017). "There is evidence that CXCR4 and its ligand, CXCL12, play a critical role in the preferential targeting of sarcoma metastases towards lung and bone." (PMID 21234386, 2011). "Several sarcoma cell lines migrated toward chemoattractant FBS and displayed invasion capacity, but only the RH30 cell line migrated and invaded specifically toward the CXCR4 ligand, CXCL12." (PMID 31428099, 2019). "Levels of IL-1β, IL-4, IL-6, CXCL5, CXCL12, CXCL14, MIF, IGF-1, TGFβ-1, and CCL21 were increased in one or more sarcoma cohorts compared with controls, and levels of IL-15 and IL-16 were significantly lower in one or more sarcoma cohorts compared to healthy controls." (PMID 41008853, 2025).
squamous cell carcinoma (5 papers, 2009 to 2025). A carcinoma arising from squamous epithelial cells. "Most cases of squamous cell carcinoma showed low expression of CXCL12." (PMID 37227446, 2023).
acute leukemia (4 papers, 2013 to 2021). A clonal (malignant) hematopoietic disorder with an acute onset, affecting the bone marrow and the peripheral blood. "In vivo imaging indicates that acute leukemia cells bind to microvascular domains in BM that express high levels of E-selectin and CXCL12 (C-X-C motif chemokine ligand 12) which may contribute, with other molecules, to foster LSC resistance to treatment and promote their survival." (PMID 31461905, 2019).
anemia (4 papers, 2023 to 2024). A reduction in the number of red blood cells, the amount of hemoglobin, and/or the volume of packed red blood cells. "Thus, the pale appearance of embryos from mothers injected with CCX771, and CCX771 plus CXCL12, is associated with anaemia." (PMID 38300826, 2024). "Concentrations of two major niche factors, SCF and CXCL1237–40, were higher in the BM fluid than those in the blood plasma but did not increase upon anemia induction, indicating that proliferation and altered lineage-choice were not due to the effect of EPO or SCF/CXCL12." (PMID 39284836, 2024).
Arterial thrombosis (4 papers, 2021 to 2025). The formation of a blood clot inside an artery. "However, a study has shown that a prevalent CXCL12 gene polymorphism linked to heightened CXCL12 production predisposes patients with chronic myeloproliferative disorders to arterial thrombosis, potentially due to the influence of VEGF." (PMID 37954596, 2023). "High levels of CXCL12 and CXCR4 on the surface of platelets are biomarkers that predict increased cardiovascular mortality due to arterial thrombosis." (PMID 37954596, 2023).
benign prostatic hyperplasia (4 papers, 2008 to 2022). A non-cancerous nodular enlargement of the prostate gland. "In these circumstances, the stromal cells can secrete proinflammatory cytokines (such as CXCL12 and CXCL5) that induce a proliferative activity of the epithelium and cause benign prostate hypertrophy (BPH)." (PMID 36139572, 2022). "The primary objective of our study was to investigate whether plasma levels of CXCL12 in PCa patients are significantly different from controls and individuals suffering from benign prostatic hyperplasia (BPH)." (PMID 25580125, 2014).
chorioamnionitis (4 papers, 2014 to 2025). A morphologic finding indicating inflammation of the fetal sac membranes. "As an example, in the chorioamnionitis, placental inflammatory lesions parallel an increase in CXCL10, CXCL11 and CXCL12 concentrations in maternal plasma." (PMID 24849800, 2014).
colon adenocarcinoma (4 papers, 2020 to 2025). "Next, to study the relation between BMP antagonist expression and CXCL12 in humans, a publicly available the cancer genome atlas (TCGA) mRNA-expression data set from a colon adenocarcinoma cohort with survival data consisting of 155 patients was used." (PMID 36326956, 2023). "Colon adenocarcinoma (COAD) stands out as a tumor characterized by particularly high levels of CXCL12 and S1P through SPHK1 activation." (PMID 40155684, 2025).
diabetic neuropathy (4 papers, 2014 to 2020). A chronic, pathological complication associated with diabetes mellitus, where nerve damages are incurred due to diabetic microvascular injury involving small blood vessels that supply these nerves, resulting in peripheral and/or autonomic nerve dysfunction. "The results of our studies suggest an important role for CXCL1, CXCL5, CXCL9, and CXCL12 in STZ-induced diabetic neuropathy." (PMID 25789329, 2015). "In diabetic neuropathy model, DRG sensory neurons acutely isolated from diabetic mice displayed enhanced CXCL12 induced calcium responses." (PMID 28720830, 2017). "In STZ-induced diabetic neuropathy, SDF-1 increased the velocity of sciatic nerve conduction, and in spinal cord injury the CXCL12 was induced in the dorsal horn after spinal cord lesioning." (PMID 25789329, 2015). "This study verifies that, in streptozotocin-induced diabetic neuropathy, the spinal protein levels of CXCL1, CXCL5, CXCL9, and CXCL12, but not CXCL11 and CXCL13, are upregulated." (PMID 25789329, 2015).
esophageal squamous cell carcinoma (4 papers, 2011 to 2021). Esophageal squamous cell carcinoma (ESCC) is a type of esophageal carcinoma (EC) that can affect any part of the esophagus, but is usually located in the upper or middle third. "Therefore, we hypothesized that there is a functional causality between CXCL12 expression and tumor progression in patients with esophageal squamous cell carcinoma (ESCC)." (PMID 27439769, 2016).
germ cell tumor (4 papers, 2011 to 2020). A benign or malignant, gonadal or extragonadal neoplasm that originates from germ cells. "Given the known influence of the microenvironment in testicular germ cell tumors we hypothesized that CXCL12 expression in stromal/inflammatory cells might also influence the final tendency for tumor cells to migrate and invade." (PMID 32758242, 2020). "Other biomarkers have been studied for their prognostic/predictive value in testicular germ cell tumors, including MIB-1, CXCL12, CXCR4 and beta-catenin." (PMID 32758242, 2020). "We aimed to assess the prognostic value of previously suggested biomarkers, related to proliferation (MIB-1 and TEX19) and to immune microenvironment (CXCL12, CXCR4, beta-catenin and MECA-79) in a surveillance cohort of stage I testicular germ cell tumor patients." (PMID 32758242, 2020).
glaucoma (4 papers, 2012 to 2024). Increased pressure in the eyeball due to obstruction of the outflow of aqueous humor. "The other examples are CCL2, IL7, CXCR3, and CXCL12, which are found in scleritis, dry eye disease, glaucoma, dry eye disease, and Sjögren’s syndrome." (PMID 31810226, 2019). "For instance, several inflammatory cytokines and chemokines, i.e., IL-6, TNF, CXCL12, and CXCL8, showed elevated centrality values in various networks, evidencing the detrimental role of neuroinflammation in glaucoma." (PMID 39458974, 2024). "Intriguingly, the results of this work have shed new light on the possible remarkable roles of AKT1, CXCL12, and HRAS genes in the pathogenesis of glaucoma." (PMID 36973823, 2023).
Hepatitis (4 papers, 2006 to 2024). Inflammation of the liver. "CXCL9 and CXCL10 mRNA expression decreased over time whereas CXCL12 recovered to its initial levels within 24 h after hepatitis induction." (PMID 26052942, 2015). "In acute T cell-induced hepatitis, CXCL12 expression was markedly down-regulated suggesting that this chemokine did not mediate hepatic T-cell recruitment during Con A-induced liver inflammation." (PMID 26052942, 2015). "Interestingly, oval cells, known to express CXCR4 as well, have been reported to migrate to the liver along a CXCL12 gradient, established by injured hepatocytes, inducing oval-cell-aided liver regeneration in hepatitis." (PMID 16819541, 2006).
inflammatory skin disease (4 papers, 2021 to 2025). Inflammatory skin disorders covers a broad category that includes many conditions ranging in severity, from mild itching to grave medical health complications These disorders are common in people of all ages and races. "Indeed, stress is known to exacerbate several inflammatory skin disorders, but little is known about the role of either Cxcl12 or melanocytes in these conditions." (PMID 40828022, 2025). "In addition, we identify the CXCR4/CXCL12 axis as a potential therapeutic target in inflammatory skin diseases." (PMID 37736772, 2023). "In summary, these results demonstrate a pivotal role of CXCR4hi neutrophils in promoting skin inflammation and suggest targeting of CXCL12/CXCR4 axis may have a role in treatment of inflammatory skin diseases." (PMID 37736772, 2023).
insulinoma (4 papers, 2014 to 2024). "We found that SAP deletion significantly promoted the growth, invasion and metastasis of malignant insulinoma through C‐X‐C motif chemokine ligand 12 (CXCL12) secreted by cancer‐associated fibroblasts (CAFs)." (PMID 38766687, 2024). "Further study indicated that CXCL12 promoted the migration and invasion of insulinoma cells by activating the p38/ERK signalling pathway." (PMID 38766687, 2024). "The promoting effect of SAP deletion on insulinoma progression was exerted mainly through CXCL12 secreted by CAFs." (PMID 38766687, 2024). "In the present study, we report the important finding that SAP deletion promotes insulinoma growth and metastasis by upregulating CXCL12, as determined using Rip1‐Tag2 and Rip1‐Tag2;SAP−/− mice." (PMID 38766687, 2024). "We found that SAP deletion promoted the secretion of CXCL12 by CAFs and that CXCL12 promoted insulinoma cell migration and invasion." (PMID 38766687, 2024). "We investigated the relationship between SAP‐silenced CAFs and activation of the CXCL12/CXCR4/p38/ERK pathway in insulinoma." (PMID 38766687, 2024). "In order to explore the beneficial effects and potential mechanisms involved in CXCL12-induced β-cell survival, human CXCL12 stable-transfected rat insulinoma Rin-5F cells (referred to as #1) were used." (PMID 24988468, 2014). "Furthermore, we demonstrate that SAP deletion‐induced upregulation of CXCL12/CXCR4 promotes insulinoma growth and metastasis by activating the p38/ERK signalling pathway." (PMID 38766687, 2024). "The results obtained in the spontaneous insulinoma mouse model suggested that CXCL12 might be involved in the promoting effect of SAP deletion on malignant insulinoma growth and metastasis." (PMID 38766687, 2024). "In addition, 30% of insulinoma patients have mutations in the YY1 gene, which regulates the transcription of CXCL12 with antidiabetic potential." (PMID 38334891, 2024). "Therefore, we evaluated the effect of CXCL12 on the p38/ERK pathway in insulinoma cells." (PMID 38766687, 2024). "We first investigated the expression of CXCR4, the receptor for CXCL12, and found that CXCR4 expression was upregulated in both NIT‐1 cells and RIN‐m5F insulinoma cells." (PMID 38766687, 2024). "Here, we found that SAP deletion promoted CXCL12 secretion by CAFs, which activated the CXCR4/p38/ERK signalling pathway, thereby promoting insulinoma growth, invasion and metastasis in Rip1‐Tag2 mice." (PMID 38766687, 2024). "CXCL12 treatment also resulted in increases in the levels of phospho‐p38 and phospho‐ERK in both NIT‐1 cells and RIN‐m5F insulinoma cells, while p38 and ERK expression did not significantly differ between PBS‐treated and CXCL12‐treated cells." (PMID 38766687, 2024).
kidney cancer (4 papers, 2002 to 2021). Primary or metastatic malignant neoplasm involving the kidney. "Regarding the kidney cancer data, the expression of CXCL12 was found to be significantly decreased (-1.15); however the underlying cause of this alteration was not high methylation, but rather, normal methylation (0.18)." (PMID 28178311, 2017). "Thus, we have investigated the expression of CXC-chemokine receptors on primary RCC cultures and on kidney cancer compared to normal kidney tissue, detecting an alteration of the CXCL12/CXCR4 signalling pathway in kidney cancer." (PMID 11953881, 2002). "In the present study, which is the first to evaluate CXCL12/CXCR4 expression and its potential function in RCC, CXCL12α expression was decreased in kidney cancer compared to normal kidney tissue." (PMID 11953881, 2002). "As the pattern of metastasis between breast and kidney cancer are comparable at least to some extent, similar mechanism of CXCR4/CXCL12 in tumour spread might also be active." (PMID 11953881, 2002).
liver cirrhosis (4 papers, 2017 to 2025). "Among them, CCR7, CXCL12, CXCR4, and CXCL8 were observed to have significantly elevated expression in liver cirrhosis samples." (PMID 41223189, 2025). "In the context of liver cirrhosis, the chemokine receptor CXCR4 and its ligands, particularly CXCL12, are crucial." (PMID 41223189, 2025). "Among them, CCL5, CXCL9, CXCL12, LCK and CD24, which are thought to participate in the immune response, were identified as the most affected genes, suggesting a disruption of the immune response in liver cirrhosis." (PMID 34434654, 2021). "Interestingly, when we re-conducted the GO analysis on overlapping DE genes in liver cirrhosis and HCC (e.g., CCR1, CXCL6, and CXCL12), the results showed that these genes were mainly enriched in the same immune response terms (especially “T cell immune process”)." (PMID 28355233, 2017).
malaria (4 papers, 2012 to 2022). Malaria is a serious and sometimes fatal disease caused by a parasite that commonly infects a certain type of mosquito which feeds on humans. "Hypothesizing that the CXCR4/CXCL12 axis would be important in this model of malaria-associated ALI/ARDS, we investigated its role." (PMID 27926944, 2016). "More specifically, the Cxcl12 expression in the liver was only minimally affected—if at all—during the prepatency phase by malaria." (PMID 35214745, 2022). "Their responses to blood-stage malaria in both vaccinated and unvaccinated mice occurred inversely with increasing expression of Cxcr4 and decreasing expression of Cxcl12." (PMID 35214745, 2022). "Our data indicate that lung pathologies in this model of malaria-associated ALI/ARDS are orchestrated by neutrophils and that CXCR4/CXCL12 are the receptor/chemokine responsible for their trafficking." (PMID 27926944, 2016). "In murine models of malaria, the supplementation of lethal infection models with CXCL12 induces a clear reduction in parasitemia." (PMID 22511975, 2012).
mantle cell lymphoma (4 papers, 2014 to 2025). Mantle cell lymphoma is a rare form of malignant non-Hodgkin lymphoma affecting B lymphocytes in the lymph nodes in a region called the ``mantle zone''. "Other studies have shown that binding of CXCL12 to CXCR4 in mantle cell lymphoma promotes the migration of the cells and is associated with an invasive disease." (PMID 24859274, 2014). "The inhibition of the 5-LOX pathway in the mantle cell lymphoma (MCL) cell line using zileuton and GSKi (FLAP inhibitor) decreased MCL cell migration towards CXCL12 (a ligand for the CXCR4 receptor) and reduced their stromal cell adhesion." (PMID 40076826, 2025).
muscular dystrophies (4 papers, 2019 to 2023). "CXCL-12 was significantly upregulated in muscular dystrophies compared to non-myopathic controls (mean 0.021 ± 0.026, P=0.03)." (PMID 37731487, 2023). "Patients with IBM displayed the highest number of double positive muscle fibers for BAFF and CXCL-12 (48%) compared to PM (25%), muscular dystrophy (3%), and non-myopathic controls (0%)." (PMID 37731487, 2023). "Both forms of myositis displayed a significantly increased number of positive fibers in comparison to muscular dystrophies (BAFF 7%, CXCL-12 10%, and double positive 3%) and non-myopathic controls (BAFF 2.9%, CXCL-12 1.2%, and double positive 0%)." (PMID 37731487, 2023).
neuroendocrine tumors (4 papers, 2016 to 2025). "In addition, CXCL12 promotes EMT-like changes and osteotropism in CXCR4 high/CXCL12 low neuroendocrine tumor (NET) cells via CXCR4." (PMID 40860192, 2025).
ovarian epithelial tumor (4 papers, 2011 to 2021). A benign, borderline, or malignant tumor that originates from the surface epithelium of the ovary. "In this study, we demonstrate the previously unappreciated constitutive expression of CXCL12 by healthy ovarian epithelial cells and ovarian epithelial tumor cells, whether benign or malignant." (PMID 21410972, 2011). "Ovarian epithelial tumor cells constitute a potent source of CXCL12." (PMID 21410972, 2011). "CXCL12 and its receptors, CXCR4 and CXCR7, have been identified as the key factors in tumor development and metastasis Ovarian epithelial tumor cells express high levels of CXCL12." (PMID 33363463, 2020). "CXCL12 was recovered from benign, borderline and malignant epithelial tumors but not from non epithelial ovarian tumors." (PMID 21410972, 2011).
Pain (4 papers, 2015 to 2024). An unpleasant sensory and emotional experience associated with actual or potential tissue damage, or described in terms of such damage. "For example, CXCL12 overexpression was found to promote neuroinflammation and cognitive dysfunction in neuropathic pain via mediating monocyte transmigration into brain perivascular space." (PMID 40115159, 2024).
Parkinson disease (4 papers, 2019 to 2023). A progressive degenerative disorder of the central nervous system characterized by loss of dopamine producing neurons in the substantia nigra and the presence of Lewy bodies in the substantia nigra and locus coeruleus. "A study showed that miR-181a-5p alleviated neuronal injury in Parkinson’s disease cell model by inhibiting CXCL12." (PMID 35793244, 2022).
peripheral vascular disease (4 papers, 2012 to 2025). Any disorder affecting blood flow through the veins or arteries outside of the heart. "Of note, the various CXC chemokines, such as CXCL4 (ELR-), CXCL5 (ELR+), CXCL6 (ELR+), CXCL12 (ELR−), CXCL13 (ELR−), and CXCL14 (ELR−), are thought to be associated with the development of SSc vasculopathy." (PMID 34774095, 2021). "Cytokine targeting may also play a future role in the therapy of peripheral vascular disease, in particular chemokine stromal-cell-derived factor-1 (SDF-1 aka CXCL12)." (PMID 23320245, 2012). "CXCR7 is an alternative receptor for chemokine stromal cell-derived factor 1 (SDF-1), also known as CXCL12, which plays significant roles in tumour growth, metastasis, and peripheral vascular diseases." (PMID 40302245, 2025).
pituitary tumor (4 papers, 2014 to 2023). A benign or malignant neoplasm affecting the pituitary gland. "CXCL12 mRNA is expressed in about 2/3 of GH-secreting pituitary tumors and NF-PitNETs, with CXCR4 mRNA expressed in almost all these tumors." (PMID 33362712, 2020). "Further study proved that CXCL12/CXCR4 mediate the DNA synthesis and cell proliferation by human pituitary tumor primary cultures." (PMID 33362712, 2020).